FOXP3 (forkhead box P3)
Diseases named in the same sentence as FOXP3 in open-access papers (continued):
Sharing a sentence is not in itself a finding about the gene and the disease.
tumor (continued). "Altogether, these results showed that the presence of cyto-nuclear ZO-1 in tumor cells correlated with an increased density of CD8+ and Foxp3+ immune cells in NCSLC." (PMID 34938731, 2021). "However, we could not find any such correlations between EGFR expression and FoxP3 mRNA expression in tumours expressing either wt or mutated forms of the EGFR." (PMID 35052732, 2021). "Tumor-infiltrating lymphocytes (TILs) were also evaluated by immunolocalizing CD3, CD8, and forkhead box protein 3 (FOXP3) in the residual tumors after NAC." (PMID 34503283, 2021). "Most immune cells infiltrating tumours are Tumour Infiltrating Lymphocytes (TILs) consisting of CD3+ Tcells (CD8+ Tcytotoxic and CD4+ Thelper cells) as well as FOXP3+ Treg cells." (PMID 33810350, 2021). "There was a strong positive correlation between the infiltration of CD20+ B cells, cytotoxic CD4+ and CD8+ T cells, regulatory FOXP3+ T cells, and CD68+ and CD163+ macrophages in both stroma and tumor nests." (PMID 33494389, 2021). "Both CD4_5 and CD4_7 had expression of regulatory T (Tregs) cell markers, with higher levels of FOXP3, IL2RA (CD25), CTLA4, and TNFRSF18 (GITR) in the tumor-predominant CD4_5." (PMID 33504936, 2021). "On the other hand, FOXP3 is essential to functional maintenance of Tregs, whose infiltration in the TME negatively regulates the immune response against tumors, favoring tumor growth and consequently related to a poor prognosis in HNC." (PMID 34201050, 2021). "We devised a simplified staining panel (DAPI, CD3, CD4, CD7, CD8, CD25, FoxP3, and PD-1) that captured the PD-1+ CD4+ T cells, tumor cells, and Tregs used to calculate the SpatialScore." (PMID 34795254, 2021). "For the Treg immune marker forkhead box protein 3 (FOXP3), in recent years, it has been proposed that overexpression of FOXP3 promotes the progression of LIHC, whereas FOXP3 knockdown inhibits tumor growth in LIHC mice." (PMID 34435618, 2021). "PD-L1 expression in tumor cells (TCs) and immune cells (ICs), CD3-positive tumor-infiltrating lymphocytes (TILs), CD8/CD3 ratios, and FOXP3-positive TILs that compose TMEs were evaluated by immunohistochemistry and classified on a score of 0-2." (PMID 33930847, 2021). "We compared the changes in tumor infiltration levels of CD4, CD8, or Foxp3‐positive T cells in tumor tissues before and after EGFR‐TKI treatment, in the patients who developed EGFR‐TKI resistance." (PMID 33305905, 2021). "Brain slices were immunologically stained for F4/80 to find tumor progression foci and Ki-67 to identify replicating tumor cells, in addition to the following T-cell phenotypic markers (CD4+, CD3+, CD8+, Foxp3, PD1)." (PMID 34944938, 2021). "Conversely, new data suggested that high Foxp3+ T cells in HCC improved the clinical outcome by suppressing proliferation, migration, and invasion of tumor cells." (PMID 34566989, 2021). "The overexpression of B7-H4 promotes the proliferation of FOXP3+ regulatory T cells and the secretion of IL-10 and TGF-β1, inhibiting antigen presentation cell function and exerting immune tolerance in tumor microenvironments." (PMID 33937019, 2021). "These CCR8+ TAM that display activated STAT3 are capable to increase the FOXP3 expression in infiltrating CD4+ T cells, suggesting the generation of iTregs that will favor tumor progression." (PMID 33924428, 2021). "Forkhead box protein P3 (FoxP3)-positive Tregs highly express OX40, CTLA-4 and CD25 and can be depleted to achieve stronger anti-tumor effects in combinatorial strategies." (PMID 33466732, 2021). "FOXP3 and IDO are known to be important immunosuppressive factors that allow the tumor to escape immunosurveillance." (PMID 33918641, 2021). "Both PD-L1 and 2 expressions on tumor cells delineate a strong positive correlation with CD3+, CD4+, CD8+, FoxP3+ cells." (PMID 32902664, 2021).
tumor (continued). "The proportion of Foxp3+CD25+ regulatory T cells (Tregs) among CD4+ T cells was nearly identical in tumors developing in p50(f/f);Lys‐Cre mice compared with WT tumor mice." (PMID 33480449, 2021). "After tumor-infiltrating lymphocytes were extracted, we analyzed PD-1 and CTLA4 expression on CD8+ T cells and Foxp3 expression in CD4+ T cells and CTLA4 expression on CD4+ T cells in the control, PTX, and PTX+US+MB groups." (PMID 34271256, 2021). "Next, we demonstrated that MSI-H CRC patients with increased IL2RB+ immune cells have an increased abundance of CD3, CD4 and FOXP3 TILs and higher PDL1 tumor and ICOS expression." (PMID 33928242, 2021). "Concomitantly, the proportion of tumor-infiltrating regulatory T cells (Tregs, CD25+ FoxP3+), a subset of CD4+ T cells that have pro-tumor influences, was reduced after ZVI@CMC treatment." (PMID 34093872, 2021). "Investigation of the TME in PC shows that immune cells with inhibitory phenotypes such as CD4+ forkhead box P3 (Foxp3+) and CD8+ FOXP3+ Tregs accumulate within the epithelial compartment the tumor margin." (PMID 34868907, 2021). "Because T cells play a critical role in tumor immunity, cytotoxic T cells (CD8+) and regulatory T cells (FOXP3+) were measured in peritumoral, conventional HCC, and sarcomatoid regions for each sample." (PMID 34081621, 2021). "Markers for T cell subsets (CD4, CD8, FoxP3), macrophages (CD68), dendritic cells (CD11c), tumor cells (CD4), vasculature (CD31), and epithelium (cytokeratin) were clearly visualized in the CODEX fluorescent images." (PMID 34795254, 2021). "We observed a statistically significant difference in FOXP3 (p = 0.03) between MGMT methylated and unmethylated tumour core, although overall counts are low (MGMTuc = 7.02 [0.51] and MGMTmc = 7.94 [0.73])." (PMID 33995529, 2021). "CCA patients with intraepithelial tumor-infiltrating CD4+, CD8+ and FOXP3+ T lymphocytes showed significantly longer overall patient survival." (PMID 34944891, 2021). "An increase was detected in the ratios of CD8+IFNγ+/CD4+FoxP3+ T cells and CD8+IFNγ+/CD11b+Ly6G+ cells in pHIFU + ICI-treated tumours relative to controls." (PMID 34229458, 2021). "TILs subsets including CD4, CD8, and FOXP3 should be evaluated, and the balance of tumor suppressive activity conferred by CD8+ Treg cells and CD4+ Treg cells and adaptive tumor responses should be determined in future experiments." (PMID 34797860, 2021). "FOXP3 is a target for identifying Tregs in the TME, contributes to Treg differentiation, and mediates tumor immune escape." (PMID 35071322, 2021). "In tumor tissues and the dLNs, anti-TNFR2 monotherapy and combinatory therapy also significantly reduced the proportion of Foxp3+ Tregs in total T cells and decreased TNFR2 expression, with the combinatory therapy showing an augmented effect." (PMID 34900985, 2021). "The tumor infiltrating lymphocytes (TILs) isolated from the tumors were stained with CD4, CD25 and Foxp3 antibodies, and the stained cells were analyzed by flow cytometry." (PMID 34183739, 2021). "Regarding the infiltration of lymphocytes in the tumor margin, we also found a high infiltration of CD3+ T lymphocytes in 59% (113/192), CD8+ T lymphocytes in 58% (107/185), and FoxP3+ T lymphocytes in 59% (114/194) of samples." (PMID 34440038, 2021). "Subsequently, we validated the protein expression level of FOXP3 and IDO in mice tumor by IHC staining." (PMID 33918641, 2021). "Regulates tumor survival, metastasis, drug-resistance, and immune escape through TGF-β-dependent conversion of FoxP3+ cells." (PMID 35096289, 2021). "Lastly, TAMs found in human renal cell carcinoma tumor can induce CTLA-4 and Foxp3 expression in T lymphocytes in vivo, further emphasizing the critical role of TAMs in cancer-related inflammation, immunosuppression, and malignant progression." (PMID 34771482, 2021). "Of note, As the original paper reported, tumor infiltrating Treg and tumor splenic Treg were sorted as live, CD45+TCRb+CD4+Foxp3+CD8-DUMP-)." (PMID 34084175, 2021).
tumor (continued). "In NCT02646748, pre- and post- therapy changes in the total number of tumor infiltrating lymphocytes and ratio of CD8+/FoxP3+ Tregs will be measured." (PMID 34512641, 2021). "In addition, murine Nrp1-deficient Tregs are associated with a profound tumor resistance due to Treg functional fragility with the acquisition of characteristic T-helper lineage markers (such as T-bet, CXCR3, IRF4 and RORγt), even if they retain their Foxp3 expression." (PMID 33924428, 2021). "Previous study reported that the expression level of Brachyury combined with status of tumor-infiltrating CD8+ and FOXP3+ lymphocytes is used to predict the therapeutic effect of radiotherapy and chemotherapy." (PMID 33734319, 2021). "The study will include analyses of CD45+CD4+CD25+FoxP3+T cells and CD25+FoxP3+T cells in the peripheral blood, as well as the distribution of CD8+ and Foxp3+ (immunoreactive/suppressor) T cells in different regions of tumor lesions." (PMID 34302324, 2021). "Tumoral PD-L1 expression correlated with intratumoral CD8+ and FoxP3+ lymphocytes, which is supportive of an adaptive immune response." (PMID 34071045, 2021). "The capacity of daily CR to decrease the frequency of Foxp3+CD8+, Foxp3+CD4+, and MDSCs is consistent with protection from the metastatic potential of tumor cells." (PMID 34707136, 2021). "Different subsets of TILs (CD8, FOXP3 and CD3 as an overall T-cell marker) in different areas of the tumour and its environment were studied." (PMID 33640523, 2021). "PD-L1+ tumours displayed higher IT and PT CD8+/PD1+ cell density compared to PD-L1- (p < 0.05), and primary IT infiltrate was enriched in CD4+/FOXP3+ cells, compared to PT regions (p = 0.004)." (PMID 33946676, 2021). "Tumor-derived single-cell suspensions were stained with antibodies specific for CD45, CD3, CD4, CD8, FoxP3, NK1.1, and CD103." (PMID 34060602, 2021). "For CD4+ helper (Foxp3-) T cells and regulatory (Foxp3+) T cells, the expression of PD-1 and TIM-3 are similar between matched MPE and tumor tissue both pre- and post-chemotherapy." (PMID 33987104, 2021). "The number of FoxP3+ Tregs and IDO+ stromal immune cells, and the coverage and intensity of IDO+ tumor cells were analysed." (PMID 34051744, 2021). "The proportion of proliferating immune cells was higher in HR- as compared with HR+ tumours (Wilcoxon, CD3+P = 0.007; CD8+P = 0.011; CD4+P = 0.009) except for Foxp3+ (P = 0.710)." (PMID 33742063, 2021). "Regulatory T cells, which cooperate in tumour development and growth, also clearly responded to ITPP treatment, as the proportion of CD45+CD4+CD25+FoxP3+ Treg cells was significantly decreased in B16F10 Luc tumours when treated with ITPP." (PMID 33624446, 2021). "Here, we found a diet-dependent positive relationship between FoxP3+CD4+ Treg cells and primary tumor area or advanced metastases." (PMID 34707136, 2021). "Nuclear localized SMAD2/3/4 complex induces tumor-promoting effects through cell proliferation (PDGF-β), immune suppression (Foxp3), EMT activation (SNAIL/SLUG, ZEB1/ZEB2, HMGA2), EMT suppression (E-Cadherin, Cytokeratin) and metastasis (HDM2, MMP-9)." (PMID 33823905, 2021). "The harvested tumor tissues were also used to conduct immunohistochemistry (IHC) analysis for the expression of the CD8+ marker for cytotoxic T‐cells and FoxP3+ for Treg cells." (PMID 33747719, 2021). "For example, HER2-enriched BCs show high tumor expression of TGF-β, a cytokine also involved in Treg differentiation from CD4+Foxp3- T cells, and of C-C motif chemokine 22 (CCL22), which is involved in Treg recruitment." (PMID 34944971, 2021). "Forkhead box protein P3 (FoxP3) improves FA uptake, oxidative phosphorylation, and FAO in Tregs and helps them survive in the lipotoxic tumor microenvironment to promote tumor growth and immune evasion." (PMID 34742349, 2021). "Patients with high 18F-FDG uptake had a significantly higher rate of PD-L1 expression, lower CD8 + tumor-infiltrating lymphocyte (TIL) counts, and higher Foxp3 + TIL counts." (PMID 33712681, 2021).
tumor (continued). "Tumor‐infiltrating CD8‐positive ICs, FOXP3‐positive ICs, CD20‐positive ICs, and IGKC‐positive ICs generally had positive correlations with each other." (PMID 33506656, 2021). "In gastric cancer, the abundance of genus Stenotrophomonas and genus Selenomonas in the gastric mucosa was positively correlated with the density of tumor-infiltrating BDCA2+pDCs and Foxp3+Tregs." (PMID 34656142, 2021). "Tumor-infiltrating lymphocytes (TILs) are important components of the tumors immune microenvironment and play a vital role in the formation and progression of tumor, including CD8+ CTLs, CD4+ Th, CD4+/CD25+/FoxP3+ Treg." (PMID 34094918, 2021). "Not only does the hypoxic tumor promote regulatory T cell (Treg) homing to the TME, but tumor-derived CD4+CD25+FoxP3+ Tregs have been found to be more suppressive of cytotoxic lymphocytes (CTLs) than normal Tregs." (PMID 33869008, 2021). "Tumor-infiltrating T cells in Bcl9-shRNA compared to NT-shRNA bearing tumors exhibited pathways enriched for TLR, FOXP3, and IL-2." (PMID 34417435, 2021). "Immunization with the BacMam-based IL-15:IL-15Rα cancer vaccine significantly delayed tumor growth by stimulating robust antitumor immune responses in tumor antigen-specific CD8+ T cells and NK cells while simultaneously attenuating Foxp3+ Treg cells." (PMID 34439192, 2021). "FOXP3 (+) T cells in the tumor nest and peri‐tumoral lymphoid stroma was significantly higher in MNCA than MNT (tumor nest, P < 0.001; peri‐tumoral lymphoid stroma, P < 0.001)." (PMID 33819365, 2021). "In this study, we used an anti-Foxp3 ASO, selected according to the results of a previous study, in which several ASOs were evaluated to improve an anti-tumor vaccine." (PMID 33801683, 2021). "The immune types were defined by the morphology of the H&E stain, whereas the distribution of the immune cell subtypes within the tumor was analyzed by IHC of CD8 and CD4 T cells, FoxP3, and CD11b." (PMID 34778030, 2021). "Tregs (FOXP3+, CD25+, CD4+) contribute to the development of an immunosuppressive tumor microenvironment, inhibiting the activation and expansion of tumor-specific effector T cells." (PMID 34829955, 2021). "Intriguingly, EZH2 expression is elevated in tumor-infiltrating Tregs, and pharmacological inhibition of EZH2 destabilize FOXP3 expression and slows tumor growth through enhancement of the recruitment and function of CD8+ and CD4+ T cells." (PMID 34069564, 2021). "Together, these data support the correlation between ECM expression, YAP activation, and high CD8+/low FOXP3+ infiltration in ESS and UUS, suggesting a mutual regulation of these components in the tumor microenvironment." (PMID 34799669, 2021). "Analysis of specific genes involved in CD4+ differentiation and function revealed differential methylation status of TBX21, GATA3, RORC, FOXP3, IL10 and IFNG in tumor CD4+ T-cells." (PMID 34012510, 2021). "Treatment also promotes an immunosuppressive tumour microenvironment through CD4+ Treg and FoxP3+ NKT cells." (PMID 34359633, 2021). "All groups receiving anti-PD1 or anti-PDL1 antibodies had CD8 T cells within the tumor, but only the combination with MSU42011 showed a reduction in the FOXP3 population of T cells within the tumors." (PMID 34638488, 2021). "Expressing Foxp3 as key transcription factor, CD4+ Tregs are mainly recruited from blood and acquire Treg phenotype and function after entering tumor tissue, exerting a significant action on immunosuppressive TME." (PMID 34625124, 2021). "Although these results are rather suggestive of an anti-tumor immune infiltrate in human NSCLC samples, we also evidenced a higher density of Foxp3+ immunosuppressive regulatory T cells in tumors with high cyto-nuclear expression of ZO-1." (PMID 34938731, 2021). "We also characterized the tumor-infiltrating lymphocytes (TILs) in tumor tissue biopsies by studying several markers (CD4, CD8, FoxP3, CD20, PD-1, and PD-L1) through immunohistochemistry (IHC) staining." (PMID 34445631, 2021).
tumor (continued). "The tumours of control and pHIFU + ICI-treated subjects showed that 2 ± 1% and 3 ± 1% of their live cells were CD3+CD4+FoxP3+, respectively, and 7 ± 4% and 10 ± 4% were CD11b+Ly6G+, respectively." (PMID 34229458, 2021). "Results demonstrated a significant reduction in tumor size and the highest levels of IFN-γ and IL-17 and the lowest levels of IL-4 FoxP3, HIF-1α, VEGF, MMP-2, and MMP-9 in the IT+IP+TEX-treated group." (PMID 34194604, 2021). "In tumor epithelium and stroma, most CD4+ T cells identified had either a Th2 (GATA-3+CD3+CD8-) or Treg (FOXP3+CD3+CD8-) phenotype, whereas only low numbers of Th1, Th17, and Tfh cells were observed." (PMID 34868011, 2021). "In contrast, mIHC-F of hPD-L1-KLN205 tumor sections showed highly significant increases in CD8+ T cells and reductions in FoxP3+ Tregs and PD-L1 expression in PDI-1-treated mice compared with vehicle-treated mice." (PMID 34054817, 2021). "For example, melanoma patients exhibited increased tumor infiltration by CD3+ CD8+ and CD3+ CD4+ and decreased CD4+ FOXP3+ Tregs after treatment with ECT plus bleomycin." (PMID 34358144, 2021). "The proportion of proliferating stromal immune cells was positively correlated with the amount of tumour area in the sample (Spearman Rho, CD3+Ki67+ = 0.397, CD8+Ki67+ = 0.331, CD4+Ki67+ = 0.414, Foxp3+Ki67+ = 0.395, P < 0.001)." (PMID 33742063, 2021). "Since metabolic tumor activity is considered to concisely reflect the tumor volume, high HIF-1 expression caused by increased tumor size may create an immunosuppressive environment in which Foxp3-regulatory T-cells (Tregs) are reported to be positively associated with MTV23–25." (PMID 32929123, 2020). "In the recent report, FoxP3 expression in tumor-infiltrating CD4+ T cells is observed to overlap with the CD69 expression, suggesting that tumor-infiltrating Treg cells are a tissue-resident population." (PMID 33379384, 2020). "Emerging evidence has shown that higher ratios of CD8+/Foxp3+ and CD8/CD4 are more sensitive indicators of prognosis and for monitoring immune function, even serving as biomarkers to predict tumour relapse and responses to treatment." (PMID 32758195, 2020). "In order to evaluate the tumor microenvironment more realistically, the ratio of infiltration of CD8+ T cells (excluding the perivascular CD8+ T cells) and the FoxP3+ T cells was deeply analyzed." (PMID 32366856, 2020). "Despite the opposite roles of T-bet and Foxp3 in the immune system and tumour biology, recent studies have demonstrated the presence of CD4+ T cells expressing both T-bet and Foxp3." (PMID 32680511, 2020). "In our previous study, we counted numbers of tumour-infiltrating CD8+ cytotoxic T cells and Foxp3+ regulatory T cells per tumour core in the same TMA as we used in the current study." (PMID 32071413, 2020). "In particular, we investigated the CD3 marker, which identifies anti-tumor immune populations, and CD163 and FoxP3, which indicate myeloid and T-cell immunosuppressive cell subsets, respectively." (PMID 32899203, 2020). "Subsets of tumor infiltrating lymphocytes (TILs) such as CD3+, CD8+, CD45RO+, FOXP3+ and PD-1+ cells were analyzed in SCLC brain metastases and four matched primary tumor specimens." (PMID 32194848, 2020). "VEGF interacts with key immune cells in the tumour micro-environment (TME), namely CD4+ forkhead box protein P3 (FOXP3) + regulatory T cells, which a strong suppressor of anticancer immunity." (PMID 32384792, 2020). "Immune subsets were characterized for CD4, CD8, FOXP3, CD20, CD33, and PD1 using immuno-fluorescence staining in stroma, tumor, and combined stroma and tumor tissue." (PMID 32150594, 2020). "Consistently, RNAseq analysis of human cancers revealed a strong positive correlation between the expression of Treg markers (FOXP3, IL2RA) and myeloid cell markers (MRC1, CD14, and ITGAM) across several tumor types." (PMID 32782249, 2020).